FLT1 (fms related receptor tyrosine kinase 1)
Diseases named in the same sentence as FLT1 in open-access papers (continued):
Sharing a sentence is not in itself a finding about the gene and the disease.
cancer (294 papers, 2007 to 2026). A tumor composed of atypical neoplastic, often pleomorphic cells that invade other tissues. "The S component samples were enriched with angiogenesis-related interactions, with high expression of VEGFA and FLT1 (encoding VEGFR1) in cancer cells and macrophages, respectively." (PMID 35874770, 2022). "The receptor of VEGF/PlGF, Fms-related tyrosine kinase 1 (Flt1), has been linked with cancer angiogenesis and found to mediate Wnt signaling pathway." (PMID 31736756, 2019). "Our FLT1 rs9582036 finding agrees with the results of previous cancer association studies." (PMID 41471344, 2025). "Fms related receptor tyrosine kinase 1, akin to Tripartite Motif Containing 14, assumes the role of a regulator in the NF-κB signaling pathway, and the aberrant functioning of NF-κB activity is implicated in the pathogenesis of inflammation-related ailments and malignancies." (PMID 39213211, 2024). "Since has 2 ligands, VEGF-A and PlGF, it is expected that the Flt-1 on CRC cells may interact with each other through VEGF/Flt-1 and/or PlGF/Flt-1-mediated signaling in a combined autocrine and paracrine way, to modulate cancer-associated vascularization and invasion." (PMID 29100318, 2017). "Cells exhibiting high expression of BCAN, GFAP, and EGFR were categorized as cancer cells, while endothelial cells displayed elevated levels of FLT1, CLDN5, and ABCG2." (PMID 41041071, 2025). "FLT1, also known as vascular endothelial growth factor receptor 1 (VEGFR1), is upregulated in various cancers and has been associated with disease progression, poor prognosis, metastasis, and recurrent disease in humans." (PMID 40558511, 2025). "Mechanistically, activated FLT1 in PARPi-resistant cancer cells promotes cell survival through AKT activation and reduced infiltration of CD8+ T cells in tumors." (PMID 38956205, 2024). "Dysregulation of the interaction between Flt-1 and VEGF has been linked to various diseases and disorders, including cancer and cardiovascular disease." (PMID 39696496, 2024). "The knockdown of Flt1 and Kdr in LFs resulted in a decrease in cancer cell migration and invasion enhanced by NRP2, indicating the essential role of VEGFR1 and VEGFR2 in the NRP2-mediated regulation of CAF activation." (PMID 38766528, 2024). "For gain-of-function experiments, we re-expressed FLT1 in FLT1-repressed cancer cells (“Flt1i + Flt1 o/e”, EV3G,H)." (PMID 38956205, 2024). "For FAP, significantly positive Pearson correlations coefficients for most cancer entities were found with prominent angiogenesis-related genes FLT1 (also known as VEGFR1), KDR (also known as VEGFR2), HIF1A, and ETS1." (PMID 36672341, 2023). "Vascular endothelial growth factor receptor-1 (VEGFR1 or FLT1) plays a role in promoting epithelial-mesenchymal transition and an aggressive phenotype in cancer cells." (PMID 37627052, 2023). "The increased expression of KDR and FLT1 complex in cancer cells and macrophages was correlated with upregulated VEGFA signaling in cancer cells in solid areas, suggesting upregulated angiogenesis and vascular reconstitution." (PMID 35874770, 2022). "Some cancer gene neighborhoods, such as GNF2_HPX, GNF2_HPN, and MORF_FLT1, were also significantly enriched." (PMID 36246406, 2022). "According to our results, SYK, KDR, and FLT1 levels in cancer tissues were 3.7 times, 1.7 times and 1.3 times higher than those in normal tissues, respectively." (PMID 35435107, 2022). "Of note, we also identified RTKs (e.g., FLT1, also known as VEGFR1) showing contrasting effects on prognoses between immune “hot” and “cold” cancers." (PMID 34479614, 2021). "FLT1, a tyrosine kinase receptor, acts as a promoter in cancer growth and metastasis, whose affinity with VEGFA is approximately ten times higher than KDR." (PMID 31383782, 2019). "Flt1 signaling in MAMs regulates a set of inflammatory genes imperative for cancer cell survival after metastatic seeding." (PMID 29455658, 2018).
cancer (continued). "Kaplan-Meier curves were generated, which showed that CRC patients with higher Flt-1 levels in the cancer had a significantly poorer overall survival." (PMID 29100318, 2017). "The present study provided pharmacoepigenomic evidence to support the importance of FLT1 in predicting the anti-cancer effects of anti-VEGF/VEGFR drugs." (PMID 26380584, 2015). "Additional clinical studies are also needed to evaluate the significance of FLT1 hypermethylation in patients with cancer who have received anti-VEGF/VEGFR drugs as second-line drugs in combination chemotherapy." (PMID 26380584, 2015). "VEGF signaling, which controls vascular function and angiogenesis that is necessary for cancer progression, appears to be decreased in Rapa-fed male and female mice, e.g., the transcripts for Vegfa and Flt1, the VEGF receptor-1, are decreased." (PMID 24409289, 2014). "Compared to Flt1, endoglin is possibly a more specific target for cancer therapy, since its expression is more tumor-related." (PMID 22929622, 2012). "Recent results in the literature have highlighted the potential key role of membrane-bound FLT1 in pathological angiogenesis, especially in the context of cancer growth and spread." (PMID 20422012, 2010). "FLT1 is a cell-surface receptor for vascular endothelial growth factors (VEGFs) A and B, which play roles in cell survival and migration as well as chemotaxis and cancer cell invasion." (PMID 41020821, 2025). "The 8 cell types were annotated based on the differentially expressed markers: Bnip3 for autophagic cancer cells, Mki67 for proliferating cancer cells, Cd14, Apoe, C1qc, Mrc1, Lyz2 for monocytes, Col3a1 for fibroblasts, Cd3e and Gzma for T cells, Flt1 for endothelial cells, and Klk1 for DCs." (PMID 38802348, 2024). "Of significance, FLT1 expression in cancer cells can be used as a biomarker to stratify patients who might benefit from combination treatment with axitinib and PARPi." (PMID 38956205, 2024). "Of the kinase inhibitor gene targets evaluated, high pre-treatment PIKFYVE, KDR, NTRK1, IKBKB, FLT1, or FGFR1 expression was each associated with lower odds of achieving CR when controlling for cancer type, biopsy site, age at the time of treatment initiation, and ICB agent." (PMID 38464258, 2024). "Among the top downregulated 50 genes, there were other cancer relevant genes such as cell cycle associated (CCNF1, CCNB1, ZWINT), cancer signaling (STK32B, IGF1, FLT1) and splicing associated (HNRNPM, HNRNPU, SRSF1) genes, which are active areas to investigate further." (PMID 38200580, 2024). "Importantly, genetic and pharmacological inhibition of FLT1 using axitinib re-sensitizes resistant cancer cells to PARPi." (PMID 38956205, 2024). "On the contrary, EPHB2, ERBB4, FGFR1, PDGFRA, KDR, and FLT1 genes showed deletion in cancer cells." (PMID 32038722, 2019). "Flt-1 was known to be expressed in endothelial cells, monocyte/macrophages, and some cancer cells." (PMID 29100318, 2017). "In methylation analysis using tissues collected from the RCC patients of the present study, FLT1 methylation showed a mean of 4 % in cancer tissues, even though that degree of methylation was significantly higher than observed in normal tissues from RCC patients." (PMID 26380584, 2015). "Finally, the relevance of FLT1 methylation for predicting the efficacy of anti-VEGF/VEGFR agents in other types of cancers should also be examined." (PMID 26380584, 2015). "IL-27 caused, in both cell lines, a significant down-regulation of a series of anti-angiogenesis related genes namely FGFR3, PTGS1 and, particularly, FLT1, which has been reported to be firmly and strongly expressed in hPCa and involved in cancer cell proliferation via autocrine VEGF signaling." (PMID 24681516, 2014). "However, FLT1 can positively regulate angiogenesis in the context of various stress responses and diseases, including cancer." (PMID 20422012, 2010).
cancer (continued). "Additionally, VEGFA released by cancer cells exhibited strong interactions with the FLT1 receptor present on M1 macrophages and follicular centre B cells, while showing diminished affinity towards FLT1 on M2 macrophages." (PMID 40429821, 2025). "Furthermore, FLT1 of LUSC, ITGB1 of DLBC, MDM4, and CDKN1A of ACC, MAPK1, and ERBB3 of UCEC, FGFR1 of ESCA, and EREG and BCL2L1 of COAD have been strongly associated with patient survival in their respective cancers." (PMID 34079798, 2021). "Therefore, the methylation status of FLT1 promoter may be useful as a new potential biomarker for cancer diagnosis." (PMID 32041578, 2020). "Among them, the peptide sequence containing F, W, and I residues at the 5, 9, and 12 positions, show a very significant nanomolar IC50 value, competing with VEGF for its receptor 1, VEGFR1 (Flt-1), which could represent a new tool within the therapeutic arsenal for cancer detection and therapy." (PMID 29143774, 2017). "FLT1 encodes a member of the vascular endothelial growth factor (VEGF) receptor, which are transmembrane tyrosine kinases involved in angiogenesis and vasculogenesis, suggesting that FLT1 may be implicated in cancer cell invasion." (PMID 28392480, 2017). "Therefore, the potential success or failure of anti-VEGF/VEGFR drugs in cancer cells originating from different tissue types and with different levels of FLT1 or KDR methylation remains unclear." (PMID 26380584, 2015). "Therefore, in addition to its role in angiogenesis, Flt-1 might mediate a variety of hitherto unappreciated biological functions, such as liver regeneration, inflammatory process and cancer metastasis." (PMID 23799978, 2013). "VEGFA ligand expressed on epithelial cells (cancer cells and AT1 cells) communicated with FLT1 (VEGF receptor 1), KDR (VEGF receptor 2), and NRP1 (a coreceptor for KDR) expressed on ECs99." (PMID 39803458, 2025). "The top 13 GDF6-related target genes (such as VEGFA, FLT1, and KDR) showed positive correlations with the tissue expression in various cancer types, suggesting a conserved regulatory network." (PMID 40699648, 2025). "In some cancer cells, changes in intracellular VEGF-VEGF-R signaling occur because of the epigenetic silencing of FLT1." (PMID 37744267, 2023). "In the mock-irradiated cancer microenvironment, there was a significant correlation between CD80 and Flt-1 (r = 0.7857, p = 0.04), and an inverse correlation between CD80 and IL-27 (r = −0.8214, p = 0.03)." (PMID 33540635, 2021). "FLT1 can combine with VEGFR-A, VEGFR-B, and FGF-2, promoting proliferation of endothelial cells in the process of angiogenesis in various cancer 22-24." (PMID 32788880, 2020). "The cancer pathway finder PCR array revealed 9 genes, including ACSL4, BIRC3,CA9, CCL2, FLT1, FOXC2, G6PD, IGFBP3 and SNAI2, with significantly altered expression in the siRNA-treated MCF-7 cells." (PMID 27478411, 2016). "Cells with mesenchymal-like morphology deriving from normal and cancer tissues showed similar levels of CD14, CD29, CD36, CD44, CD45, CD49e, CD73, CDw90, CK18, FLT-1, STRO-1, SH4, HLA-ABC, and integrin α2β1 expression." (PMID 22330345, 2012). "In particular, FLT1 is the main receptor for VEGFB and PlGF induced signaling and is over-expressed in several cancer cells." (PMID 20422012, 2010). "Unlike the known role of VEGF signaling in angiogenesis, we demonstrate a novel, non-canonical role for FLT1 signaling that protects cancer cells from PARPi in-vivo through a combination of cell-intrinsic and cell-extrinsic pathways." (PMID 38956205, 2024). "For example, we identified the driver gene set including ATR, COL4A2, and FLT1 in GBM individual TCGA‐12‐0821, and the Dscores of dysfunctional cancer hallmarks showed significant correlation with Escores of these cancer hallmarks (PCC = 0.86 and P = 1.25e‐08)." (PMID 37491836, 2023). "FLT1 could be described as a therapeutic target in inflammatory events whereas EGFR is known as a key regulator in cell division and cancer development." (PMID 36899812, 2023).
cancer (continued). "In addition to CD276 (B7-H3), FLT1 (VEGFR1) appeared in both C3 and C4 networks and was highly expressed in ACC compared with that in other cancers." (PMID 34194394, 2021). "Although different subgroups of ccRCC were not studied here, significant differences were found in the angiogenesis-related genes FLT1, FLT4, and KDR between cancer and benign EVs as well as ccRCC EVs and pRCC EVs, which fits more with a lower aggressive ccA phenotype." (PMID 34331598, 2021). "In terms of FLT1, it was found to be downregulated in the German Shepherd carcinomas in tumors without metastasis." (PMID 34679042, 2021). "Another hub gene, such as KITLG, PTGS2, SYK, FLT1 (VEGFR-1), GNA13, etc. could also regulate invasion and metastasis of cancer 42-48." (PMID 32194783, 2020). "As a result, the interaction of VEGF with Flt-1 (VEGFR-1) and KDR (VEGFR-2) receptors on the surface of the endothelial cells is inhibited, which leads to the reduction of vascularization and inhibition of cancer growth." (PMID 31547532, 2019). "ANGPT2, FLT1, and ESM1 are pro-angiogenic genes, with ANGPT2 and FLT1 playing a role in enhancing sprouting angiogenesis, and ESM1being upregulated in hypervascularised cancers." (PMID 31665941, 2019). "However, FLT1 (normal, 1.3 %; cancer tissue, 4.4 %; p = 0.023) and KDR (2.2 % vs. 16.4 %; p = 0.008) methylations were significantly higher in cancer tissues, compared to normal tissues." (PMID 26380584, 2015). "However, in some cancer cells, changes in intracellular VEGF-VEGFR signaling occur due to epigenetic gene silencing of FLT1 and KDR." (PMID 26380584, 2015). "Importantly, most of these identified genes, such as FLT1, EBI3, LEP and BCL6, are highly involved in angiogenesis and immune modulation in malignant tumor progression." (PMID 22929622, 2012). "VEGF isoforms have different affinities for the VEGF receptors [VEGFR1 (flt1), VEGFR2 (KDR/flk1) and VEGFR3 (neuropilin)] and may play distinct roles in vascular development and diseases such as cancer growth and metastasis." (PMID 19922608, 2009). "The combined expression of PLGF, HIF-1α, VEGFR1 (FLT1 gene), and PD1 was associated with several cancer hallmarks, regardless of cancer type, including tissue invasion and metastasis, sustained angiogenesis, persistent proliferative signaling, immune evasion, and reprogramming of energy metabolism." (PMID 39457506, 2024). "In addition, VEGFA and B, their receptors KDR and FLT1, and downstream TFs, including KLF4 and ETS1, were found in this analysis as targets of cooperative ENHs, in line with the pivotal role of angiogenesis in promoting cancer metastatic spreading." (PMID 37408506, 2023). "This increase in Flt1 expression in PE could derived from dual role of Flt1 in angiogenesis, a negative role in early embryogenesis and a positive role in cancer and other diseases." (PMID 26221124, 2015). "Important cancer related genes identified for this phenotype are CDK6 gene, which inhibits proliferation of human mammary epithelial cells; SIAT4C, which is down-regulated in RCC, RHOB, which is known to be a pro-apoptotic and tumor suppressor gene, and the FLT1 and TFF3 gene." (PMID 19458770, 2007).
infection (20 papers, 2012 to 2026). The state of being infected such as from the introduction of a foreign agent such as serum, vaccine, antigenic substance or organism. "We also identified immune/inflammatory response markers associated with aGVHD (IL-9, Eotaxin-3), cGVHD (Flt-1), infection (D-dimer), or relapse (IL-17D, bFGF, Eotaxin-3)." (PMID 35700185, 2022). "Vascular cells shared six down-regulated DEGs in response to either Aβ pathology or MA10 infection, (Rgs5, Slc1a2, Flt1, Sparcl1, Bsg, Pecam1)." (PMID 41497643, 2025). "We also demonstrated that Vegfb or Flt1 deletion led to a decrease in the proportion of memory precursor effector cells in antigen-specific T cells on day 7 after prime infection." (PMID 39145452, 2024). "Consistent with the results of Vegfb knockdown by lentivirus, Vegfb or Flt1 knockout resulted in a weakened antigen-specific response on day 7 of prime infection, and the survival of antigen-specific T cells decreased, starting at the contraction phase after 21 days." (PMID 39145452, 2024). "Furthermore, Vegfb or Flt1 knockout resulted in a reduced antigen-specific recall of memory T cells after 7 days of challenge infection." (PMID 39145452, 2024). "The levels of Ang-1, Ang-2, IFN-α, IFN-γ and VEGF R1/Flt1 were unaffected by infection." (PMID 23155405, 2012). "We therefore first determined the levels of a panel of markers (IL-1β, IL-6, IL-8, IL-10, IL-12p70, TNF, RANTES, MIG, MCP-1, IP-10, IFN-α, IFN-γ, Ang-1, Ang-2, uPAR and VEGF R1/Flt1) in the plasmas of 79 women who remained infection-free from inclusion through to delivery." (PMID 23155405, 2012). "Then, we adoptively transferred Vegfb- or Flt1-cKO and WT CD8+ OT-1 T cells to recipient mice, followed by prime and challenge infection with LM-OVA." (PMID 39145452, 2024). "Adenoviral constructs containing VEGF, DR5, FLT-1 and survivin promoter driving lacZ, GFP and luciferase reporter genes were used for infection of D54 MG cells." (PMID 28251571, 2017). "At 36 h post infection, there was a clear colocalization of the NS2B protein with Cav-1 and Flt-1 in a high percentage of cells, although the distribution varied slightly between cells." (PMID 24643062, 2014). "Using this model system of immune-mediated BBB disruption, we have demonstrated that intracranial TMEV infection alters expression of flk-1, but not flt-1, mRNA in the CNS." (PMID 22985494, 2012). "Unlike flk-1 mRNA expression, flt-1 mRNA expression in the hippocampus and striatum remains unaltered 7 days post-TMEV infection." (PMID 22985494, 2012).
cardiovascular diseases (9 papers, 2016 to 2026). "Since endoglin is mainly expressed in endothelial cells, circulating soluble endoglin levels have been investigated in association with cardiovascular diseases, as with soluble Flt-1." (PMID 29937525, 2018). "To date, studies of the variants in FLT1 have been conducted mostly in non-cardiovascular diseases." (PMID 27736948, 2016). "The HIF-1 signaling pathway is closely related to hypoxia–ischemia in cardiovascular diseases, and we found four genes (FLT1, KDR, ANGPT2, and PGF) related to angiogenesis in the pathway." (PMID 36435742, 2022). "This review focuses on a novel concept wherein the development of CKD-associated cardiovascular diseases is associated with noninfectious inflammation mediated by the signaling pathway of placental growth factor (PlGF) and its receptor, fms-like tyrosine kinase-1 (Flt-1)." (PMID 36430665, 2022). "Through the interaction with endothelial cell membranes and FLT1, KDR or NRP1 receptors and the subsequent activation of RAS and MAPK kinases signalling cascades, VEGF is a powerful inducer of angiogenesis, which can have a very important role in cardiovascular diseases." (PMID 35736920, 2022).
adenocarcinoma (7 papers, 2012 to 2024). A common cancer characterized by the presence of malignant glandular cells. "Electroporation of VEGFR1_MOe13 directed against the human FLT-1 transcript increases soluble FLT-1 RNA and decreases membrane FLT-1 RNA in both adenocarcinoma lines." (PMID 22438952, 2012). "In this study, we examined the expression of EpoR and Akt in adenocarcinoma cells as well as EpoR, VEGF, Flt-1, and CD31 expression in xenografts." (PMID 27543111, 2016).
metabolic disorders (3 papers, 2021 to 2024). "Multiple groups have reported that stimulation of angiogenesis in adipose tissue of obese rodents by increasing angiogenic gene expression (e.g., VEGFA, VEGFB, FLT1, FOXO, Angiopoietin2) not only improves local adipose tissue function, but also counteracts systemic metabolic disorders." (PMID 34660572, 2021).
retinopathies (2 papers, 2021 to 2023). "Elevated miR-223-3p showed increased expression of angiogenic markers, VEGF, FLT-1 and KDR compared to controls at 2% glucose, confirming its role in zebrafish retinopathy in the developmental stage." (PMID 36869348, 2023).